RNU6-407P (RNA, U6 small nuclear 407, pseudogene)
Gene: Small nuclear RNA gene on chromosome 20 (35,030,317 to 35,030,420, reverse strand). Ensembl gene ENSG00000202150.
Homologues: Orthologues: chimpanzee U6 (94% identical). Paralogues in human: RNU6-29P (89% identical), RNU6-41P (89% identical), RNU6-1011P (88% identical), RNU6-1117P (88% identical), RNU6-379P (88% identical), RNU6-38P (88% identical), RNU6-529P (88% identical), RNU6-1075P (88% identical), RNU6-12P (88% identical), RNU6-13P (88% identical), RNU6-242P (88% identical), RNU6-25P (88% identical), and 1287 more.